SERPINA3 (serpin family A member 3)
Diseases named in the same sentence as SERPINA3 in open-access papers (continued):
Sharing a sentence is not in itself a finding about the gene and the disease.
glioblastoma (13 papers, 2021 to 2025). The most malignant astrocytic tumor (WHO grade IV). "SerpinA3 was also associated with tumor invasiveness as a consequence of remodeling the extracellular matrix, as shown in studies using melanoma and glioblastoma." (PMID 38279150, 2024). "Various clinical trials have demonstrated that the high expression of SERPINA3 is an independent prognostic factor of the OS rate of patients with glioblastoma, and that it is associated with poor prognosis and tumor recurrence." (PMID 34859010, 2021). "SERPINA3 is highly secreted from reactive astrocytes and found in amyloid plaques, as well as many types of tumors including glioblastoma, and shown to promote proliferation and survival of cancer cells." (PMID 37369719, 2023). "Elevated SERPINA3 has been studied for many years due to its connection with neurological diseases such as Alzheimer’s, glioblastoma and multiple sclerosis." (PMID 35328776, 2022). "In terms of downregulated genes in glioblastoma, we found NDRG4, SERPINA3, RPN2, VIM, and TIMP1 to be differentially the most downregulated genes." (PMID 38769480, 2024). "The high expression of SERPINA3 has been suggested to be associated with tumorigenesis of colorectal carcinomas, liver hepatocellular carcinoma (HCC), lung cancer, glioblastoma (GBM) and gastric cancer." (PMID 33569740, 2021).
atherosclerosis (12 papers, 2018 to 2025). A disease characterized by the build-up of fatty material and calcium deposition in the arterial wall resulting in partial or complete occlusion of the arterial lumen. "SERPINA3 is associated with a variety of metabolic disorders (e.g., non-alcoholic fatty liver disease, obesity, and atherosclerosis) through the regulation of inflammatory factor release and endothelial dysfunction." (PMID 40076571, 2025). "The observed elevated level of the SERPINA3 protein in atherosclerosis may be associated with the remodeling of atherosclerosis plaques and their stability, which increases the risk of a heart attack." (PMID 36672665, 2023). "In particular some studies demonstrated that TREM2 is protective for atherosclerosis, while the increase of the presence of some other proteins, like SERPINA3 and C7 led to an increase of cardiac mortality and coronary artery disease respectively." (PMID 40758327, 2025). "We identified several genes, including Cemip, Lum, Mfge8, Spp1, and Serpina3, which are known to be involved in atherosclerosis-induced gene expression." (PMID 38289873, 2024). "An in vitro study using an atherosclerosis model demonstrated an increase in SerpinA3 expression in aortic smooth muscle cells exposed to oxidized LDL." (PMID 38279150, 2024). "Genes such as FCN1, IL1B, and SERPINA3 are involved in immune cell infiltration and regulate atherosclerosis (AS) through ceRNA." (PMID 36686646, 2022). "SERPINA3 belonging to the superfamily of serine protease inhibitors plays a significant role in the pathogenesis of atherosclerosis." (PMID 36082132, 2022). "Ox-LDL stimulated RASMCs, as an in vitro model for atherosclerosis, were detected to express more SERPINA3 in mRNA level and protein level." (PMID 34957248, 2021). "To clarify the function of SERPINA3 in atherosclerosis, we used siRNA oligomer and ox-LDL in RASMCs." (PMID 34957248, 2021). "In this study, we evaluated the association between plasma SERPINA3 levels and CAD and explored the mechanism of SERPINA3 in the pathogenesis of atherosclerosis." (PMID 34957248, 2021). "This further demonstrates that smooth muscle cells expressing SERPINA3 contribute to the progression of atherosclerosis." (PMID 34957248, 2021). "To clarify the role of SERPINA3 in atherosclerosis, we used siSERPINA3 oligomer and ox-LDL in RASMCs." (PMID 34957248, 2021). "This study demonstrated that plasma SERPINA3 levels were significantly increased in patients with CAD, and SERPINA3 also played an essential role in the pathogenesis of atherosclerosis." (PMID 34957248, 2021). "SERPINA3 expressed by RASMCs promoted cell proliferation, migration, and expression of inflammation cytokines in atherosclerosis via NF-κB signaling pathways in RASMCs." (PMID 34957248, 2021). "In summary, secreted SERPINA3 may increase the expression of inflammatory factors and immunocyte adhesion factors in endothelial cells to participate in atherosclerosis." (PMID 34957248, 2021). "Based upon these, it was hypothesized that SERPINA3 may act as a pro-inflammatory effect and contribute to atherosclerosis." (PMID 34957248, 2021). "Besides, in vitro model of atherosclerosis displayed stimulation with ox-LDL increased the expression of SERPINA3 in RASMCs." (PMID 34957248, 2021). "As for the source of SERPINA3, on the one hand, SERPINA3 is secreted by the liver as reported in previous studies, because the atherosclerosis occurrence is often accompanied by systemic changes and is correlated with metabolic liver diseases through multiple pathophysiological mechanisms." (PMID 34957248, 2021). "Hence, we conducted a clinical study to explore the relationship between plasma SERPINA3 levels and CAD and experimental research to reveal the role of SERPINA3 in the pathogenesis of atherosclerosis." (PMID 34957248, 2021). "Therefore, SERPINA3 played an essential role in the pathogenesis of atherosclerosis." (PMID 34957248, 2021).
atherosclerosis (continued). "Thus, SERPINA3 played a significant role in the pathogenesis of atherosclerosis." (PMID 34957248, 2021). "However, the association between plasma SERPINA3 levels and CAD and the mechanism of SERPINA3 in the progression of atherosclerosis are still unknown." (PMID 34957248, 2021). "Levels of SerpinA3 in the plasma were increased in coronary artery disease (CAD) patients and correlated with the extension of atherosclerosis." (PMID 38279150, 2024). "Further studies should focus on exploring the source of plasma SERPINA3 in CAD patients and the impact of plasma SERPINA3 on atherosclerosis." (PMID 34957248, 2021). "However, SERPINA3 worked more efficiently in combination with ox-LDL, verifying its ability was amplified in atherosclerosis." (PMID 34957248, 2021). "The gene list included well-known atherosclerosis-associated genes Serpina3,42Cemip,43Thbs1,44Lum,45 and Spp146,47 but also novel genes without previous association to SMC function in atherosclerosis, such as Anxa4, Cd276, Itih4, Myof, Pcdh11x, Rab31, Serpinb6b, Slc35e4, Slc8a3, and Spink5." (PMID 38289873, 2024).
Sepsis (11 papers, 2020 to 2026). Sepsis is defined as life-threatening organ dysfunction caused by a dysregulated host response to infection. "Recently, it has been reported that the levels of glycopeptides and glycosylation remodeling associated with SERPINA3 increase substantially during the development of sepsis and sepsis-induced ALI." (PMID 37197655, 2023). "To interrogate the roles of SERPINA3 in clinic, we collected peripheral blood samples and enriched monocytes from 15 sepsis patients and 15 healthy volunteers." (PMID 36864027, 2023). "Although little is known about the roles of NFYC, TNFRSF8 and SERPINA3 in sepsis, NFYC is characterized as a new regulator of skeletal muscle immunometabolic signaling." (PMID 36650470, 2023). "In monocytes of sepsis, the status of SERPINA3 being positively correlated with m6A levels showed a negative correlation with cytokines expression." (PMID 36864027, 2023). "In the end, we managed to formulate a signature of 7 IRGs for the prognosis of sepsis patients: − 0.465 × CCL5 + 0.215 × DEFA4 − 1.487 × NFYC + 1.055 × ESR1 − 0.737 × TNFRSF8 − 0.228 × CX3CR1 + 1.003 × SERPINA3." (PMID 36650470, 2023). "In sepsis, changes in the SERPINA3 protein glycosylation are reversed." (PMID 36672665, 2023). "The monitoring of SERPINA3 protein glycosylation in routine diagnostics could allow for much earlier detection of sepsis development and perhaps more effectively inhibit it." (PMID 36672665, 2023). "Proteomic analysis revealed that faulty functionality of neutrophils may be due to the autophagy proteins i.e., DNAJC13, AHSG, TMSB4X, PROS1 and SERPINA3, which can be used as therapeutic targets in decompensated cirrhosis patients with sepsis." (PMID 35681439, 2022). "We conclude that the faulty functionality of neutrophils may be due to the autophagy proteins, i.e., DNAJC13, AHSG, TMSB4X, PROS1, and SERPINA3, which can be used as therapeutic targets in decompensated cirrhosis patients with sepsis." (PMID 35681439, 2022). "In addition, several studies have shown that SELL and SERPINA3 are also associated with sepsis, but it was not confirmed in our present study." (PMID 36650427, 2023). "However, few downregulated proteins in sepsis patients compared to HC were AHSG, and PROS1, whereas compared to w/o sepsis, patients were AHSG, PROS1, DEFA1, SERPINA3, MPO, and MMRN1 (Azurophil granule, azurophil granule lumen and secretory granule lumen (GO:0042582, GO:0035578 and GO:0034774))." (PMID 35681439, 2022).
endometrial cancer (10 papers, 2017 to 2025). Primary or metastatic malignant neoplasm involving the endometrium (mucous membrane that lines the endometrial cavity). "High expression of the SERPINA3 gene is also associated with poor prognosis, low differentiation, malignancy, and high-stage endometrial cancer." (PMID 36672665, 2023). "SERPINA3 has been associated with endometrial cancers and undifferentiated carcinoma with osteoclast-like giant cells, a rare pancreatic cancer." (PMID 32024004, 2020). "In the present study, biological analysis showed that SERPINA3 is highly enriched in multiple immune‐related terms, including activation, differentiation, and proliferation of T cells, which was in accordance with a previous study on endometrial carcinoma." (PMID 34449972, 2021). "Genes, such as SERPINA3, BIRC3, and CREBRF, are liable for the proliferation of various cancer cells, such as endometrial cancer and gastric cancer, but these genes may be linked with the proliferation of BRCA cells." (PMID 31311202, 2019). "SERPINA3 was reported to play a role on migration of endometrial cancer cells." (PMID 27213583, 2017). "Interestingly, SERPINA3 is a useful biomarker in the prognosis of different solid tumors, including endometrial cancer: in this histotype, SERPINA3 expression is significantly correlated with the worst pathological grade, lymph node metastasis (LNM) grade, and clinical stage." (PMID 33266496, 2020).
hepatocellular carcinoma (10 papers, 2009 to 2026). A malignant tumor that arises from hepatocytes. "Circ SERPINA3 expression is elevated in hepatocellular carcinoma and suppresses the antitumor activity of miR 944, reducing patient survival by approximately one year." (PMID 41465470, 2025). "Recombinant IL-6 (rhIL-6) treatment can stimulate SerpinA3 synthesis in human hepatoma cell lines." (PMID 37288300, 2023). "Therefore, we further investigated, if SERPINA3 upregulation is STAT3-dependent, since SERPINA3 has been shown to be a prototypic acute phase molecule up-regulated upon OSM stimulation in hepatoma cells as also demonstrated in IEC in our microarray experiments." (PMID 24710357, 2014). "Moreover, co-immunoprecipitation of HNRNP-K with SERPINA3 correlated with levels of HIST2H2BE transcripts and telomere length in hepatocellular carcinoma (HCC) tissues." (PMID 32457836, 2020).
diabetes (9 papers, 2019 to 2025). "After controlling for age, NIHSS, hypertension, diabetes, infarct volume, triglyceride, previous stroke, and toast classification, an elevated level of SERPINA3 was associated with a higher degree of CSO‐EPVS (OR, 3.06; 95% CI, 1.04–9.01; p = 0.042)." (PMID 37721405, 2024). "With ongoing advances in molecular biology and drug development technologies, SERPINA3-specific interventions are expected to broaden the horizons for the comprehensive management of diabetes and its related complications." (PMID 40076571, 2025). "RT-PCR results showed that the relative SERPINA3 mRNA expression levels in proximal tubular epithelial cells (HK-2 cells) stimulated with high glucose to mimic diabetes in vitro were significantly higher than those in the normal control group." (PMID 36304455, 2022). "We further discovered marked changes in prediabetes/diabetes-related proteins (AACT/SERPINA3, AAT/SERPINA1, ApoA-I, HP, RBP4, TTR, and ZAG)." (PMID 31504048, 2019). "Contrary to the results of animal studies, SERPINA3 was significantly decreased in patients with prediabetes/diabetes in our study." (PMID 31504048, 2019). "Our research has established the pivotal role of SERPINA3 in diabetes-related cognitive impairment, suggesting that the modulation of this gene or its associated signalling pathways may provide novel approaches for DCI prevention, diagnosis, and treatment." (PMID 40076571, 2025). "On the basis of these findings, we hypothesised that inhibiting or regulating SERPINA3 could be a potential starting point for intervention in diabetes-related complications and delaying the process of DCI." (PMID 40076571, 2025). "Therefore, we inferred a correlation between SERPINA3 and chymase secreted from mast cells, which jointly regulate the progression of diabetic renal tubular injury." (PMID 36304455, 2022). "However, no significant linear or nonlinear association has been found between SERPINA3 level and acute infarct volume (>1.9 mL) after adjusting for age, hypertension, diabetes, smoking, drinking and TOAST classification (p for nonlinearity = 0.7745, p for linearity = 0.8173)." (PMID 37721405, 2024). "The present study confirmed the upregulation of SERPINA3 in DCI samples, which corresponds to the combined state of elevated systemic inflammatory levels, increased insulin resistance, and impaired cerebral microvascular function in patients with type 2 diabetes mellitus." (PMID 40076571, 2025). "SERPINA3 decreased after bariatric surgery only in the control and diabetes remission groups, suggesting an improvement in their inflammatory status that apparently did not occur in the subjects with persistent diabetes." (PMID 34501327, 2021). "In contrast, growth-inhibiting protein 25 (GIG25/AACT/SERPINA3), albumin (ALB), and transthyretin (TTR) were expressed at lower levels in normal patients with abdominal obesity (Group 2), prediabetes (Groups 3 and 4), and diabetes (Groups 5 and 6) than in normal patients (Group 1)." (PMID 31504048, 2019). "The abundance of SERPINA3 (spots 1235 and 1244), F2 (spot 928), and GSN (spot 1030) decreased after surgery in the non-diabetic (all spots) and diabetes remission groups (except for spot 1235), whereas no changes were observed in the persistent diabetes group." (PMID 34501327, 2021).
myocardial infarction (9 papers, 2020 to 2025). Gross necrosis of the myocardium, as a result of interruption of the blood supply to the area, as in coronary thrombosis. "SERPINA3 not only was a novel diagnostic and pharmacological target for HF but also associated with major adverse cardiovascular events in patients with acute myocardial infarction." (PMID 36082132, 2022). "In clinical practice, elevated circulating human SerpinA3 levels were significantly associated with adverse cardiovascular events after acute myocardial infarction (AMI), suggesting that human SerpinA3 may be a potential predictive marker for clinical manifestations of AMI." (PMID 37288300, 2023). "In another study, SERPINA3 was identified as a potential predictive marker of clinical outcome after myocardial infarction, as the level of this protease inhibitor was found to be directly correlated with other measured inflammatory markers." (PMID 38379859, 2023). "MZF1 is a transcriptional regulator of several proteins; one of them is the SERPINA3 (serine proteinase inhibitor A3), protein that has been recently suggested as a potential predictive marker of clinical outcomes in myocardial infarction." (PMID 31947776, 2020). "SERPINA3 is mainly involved in the acute phase response, inflammation, and proteolysis, it could be utilized as a biomarker for the prognosis and diagnosis of several diseases, including myocardial infarction, various cancers, and neurodegenerative diseases." (PMID 37197655, 2023). "Although total cholesterol was found to be predictive for SERPINA3 values in patients presenting with myocardial infarction previously, we did not observe this in our population." (PMID 40087712, 2025).